SLC26A8 (solute carrier family 26 member 8)
Description:
Antiporter that mediates the exchange of sulfate and oxalate against chloride ions across a membrane. Stimulates anion transport activity of CFTR. May cooperate with CFTR in the regulation of chloride and bicarbonate ions fluxes required for activation of the ADCY10/PKA pathway during sperm motility and sperm capacitation (By similarity). May play a role in sperm tail differentiation and motility and hence male fertility (By similarity).
Synonyms: TAT1; AZON; SPGF3
Tractability: Antibody: its Gene Ontology location is reachable by antibodies, with high confidence; UniProt predicts a signal peptide or a membrane-spanning region.
Gene: Protein-coding gene on chromosome 6 (35,943,516 to 36,028,767, reverse strand). Ensembl gene ENSG00000112053.
Subcellular location: Membrane
Subcellular location (Human Protein Atlas): Annulus; Acrosome
Gene Ontology:
Molecular function: chloride channel activity; oxalate transmembrane transporter activity; protein binding; sulfate transmembrane transporter activity; sulfate:chloride antiporter activity; chloride:bicarbonate antiporter activity
Biological process: chloride transport; oxalate transport; sulfate transmembrane transport; chloride transmembrane transport; transmembrane transport
Cellular component: membrane; plasma membrane; sperm annulus
Genetic constraint (gnomAD): Loss-of-function variants: 64 observed, 100.1 expected, observed/expected ratio (o/e) 0.64, 90% interval 0.52 to 0.79. The upper end of that interval is the gene's LOEUF score, 0.79, which puts it in group 3 of 6, group 1 being the genes least tolerant of losing a copy. Missense variants: 945 observed, 1,176.7 expected, observed/expected ratio (o/e) 0.8, 90% interval 0.76 to 0.85. Synonymous variants: 398 observed, 437.31 expected, observed/expected ratio (o/e) 0.91, 90% interval 0.84 to 0.99.
Homologues: Orthologues: chimpanzee SLC26A8 (98% identical), macaque SLC26A8 (95% identical), dog SLC26A8 (72% identical), rabbit SLC26A8 (70% identical), pig SLC26A8 (68% identical), rat Slc26a8 (67% identical), mouse Slc26a8 (66% identical), guinea pig SLC26A8 (61% identical). Paralogues in human: SLC26A3 (23% identical), SLC26A6 (22% identical), SLC26A4 (22% identical), SLC26A5 (21% identical), SLC26A9 (21% identical), SLC26A2 (18% identical), SLC26A1 (17% identical), SLC26A7 (17% identical), SLC26A11 (13% identical).
Diseases named in the same sentence as SLC26A8 in open-access papers:
SLC26A8 is named in the same sentence as 18 diseases in open-access papers, as found by Europe PMC text mining. Sharing a sentence is not in itself a finding about the gene and the disease. The quoted sentences say what the papers report.
asthenozoospermia (12 papers, 2015 to 2024). "It was also clear that the missense mutation in SLC26A8 was associated with human asthenozoospermia." (PMID 32487021, 2020). "Variants in SLC26A8 have been implicated to cause asthenozoospermia (reduced sperm motility) via altered interaction with CFTR (cystic fibrosis transmembrane conductance regulator)." (PMID 26261983, 2015). "Gene SLC26A8 is a sperm-specific member of the SLC26 family, and its heterozygous missense mutations are highly associated (power of >95%) with asthenozoospermia." (PMID 35711794, 2022). "Consistent with this, most individuals carrying heterozygous variants in SLC26A8 and SLC26A3 also presented with mild asthenozoospermia phenotype." (PMID 35409285, 2022). "Genetic defects in CatSper1/2 and in the sperm-specific anion exchanger SLC26A8 that associates with the CFTR channel, have been identified in patients affected by distinct types of asthenozoospermia." (PMID 34205849, 2021). "Importantly pathogenic gene variants in SLC26A8 and SLC26A3 were reported to induce human asthenozoospermia and male subfertility." (PMID 35409285, 2022). "Unlike the sperm-specific SLC26A8, the loss of which causes complete lack of sperm motility and reduced sperm fertilization potential in mice and asthenozoospermia in humans, the role of SLC26A3 in regulation of male fertility is more complex." (PMID 29079751, 2017). "Indeed, nearly all pathogenic gene variants that have been described to contribute to asthenozoospermia and male infertility in humans (CASTSPER, SLC26A3, SLC26A8, SLC9C1, VDAC, SLO3) were supported by studies using KO mouse models that show a similar phenotype and pathology." (PMID 35409285, 2022).
male infertility (4 papers, 2018 to 2023). The inability of the male to effect fertilization of an ovum after a specified period of unprotected intercourse. "SLC26A8 functional relevance is linked to sperm motility and mutations appear to cause male infertility." (PMID 38006387, 2023). "One of the most intriguing results was the identification SLC26A8 linked to male infertility as an mRNA predictor in all LEN proposed gene combinations." (PMID 38006387, 2023). "Heterozygous SLC26A8 variants were shown to be associated with human male infertility in two patients with moderate asthenoteratozoospermia and a third characterized by severe asthenoteratozoospermia and reduced sperm count." (PMID 35409285, 2022). "Generation of Slc26a8 knockout (KO) mice results in male infertility due to decreased sperm motility, but mouse viability is not affected." (PMID 38111663, 2023).
Infertility (3 papers, 2022 to 2024). "However, the presence of two missense mutations in two different positions in one of the patients was sufficient to cause infertility and a loss of SLC26A8." (PMID 39676174, 2024). "Hence Slc26a8 null mice showed infertility due to the complete loss of sperm motility and impaired fertilization potential—capacitation and acrosome reaction." (PMID 35409285, 2022).
rosacea (3 papers, 2023 to 2026). A chronic erythematous skin disorder that affects the face. "Furthermore, through whole‐genome sequencing, researchers identified three genes—LRRC4, SH3PXD2A, and SLC26A8—each of which has rare genetic variations associated with susceptibility to rosacea within families, indicating these genes as potential susceptibility genes." (PMID 41437844, 2026). "Collectively, these data further highlight SH3PXD2A, SLC26A8 and LRR family genes as potential candidate genes for rosacea susceptibility." (PMID 37402769, 2023). "The relevance of SH3PXD2A, SLC26A8 and LRR family genes in rosacea predisposition is underscored by presence of additional variants in independent families." (PMID 37402769, 2023). "In the present study, based on WGS of 3 large rosacea families (as discovery cohort) and WES of 49 additional small rosacea families (as validation cohort), we identified LRRC4, SH3PXD2A, and SLC26A8, each with a single rare genetic variant, as potential candidate genes for rosacea susceptibility." (PMID 37402769, 2023).
colitis (2 papers, 2022 to 2025). Inflammation of the colon. "WB and immunofluorescence experiments confirmed that the expression levels of MMP-9, PTGDS, SLC26A8, and CD160 in colitis were significantly increased, whereas that of TLR5 were decreased." (PMID 36733384, 2022). "The expression of MMP-9, PTGDS, SLC26A8, and CD160 in colitis was increased in the IBD mouse model, whereas the expression of TLR5 was downregulated." (PMID 36733384, 2022). "Screening of disease markers for colitis in mice using a machine-learning approach revealed that the expression levels of SLC26A8, MMP9, PTGDS, and CD160 were significantly elevated in colitis tissues, whereas the expression level of TLR5 was significantly reduced." (PMID 40110435, 2025).
colorectal cancer (2 papers, 2021 to 2022). A primary or metastatic malignant neoplasm that affects the colon or rectum. "A study has shown that SLC26A8 is a susceptibility gene for hereditary non-polyposis colorectal cancer, which also provides reference for our subsequent research on the development of IBD for colorectal cancer." (PMID 36733384, 2022).
asthma (1 paper, 2023). "Increased levels of SLC26A8 are associated with asthma and lower sperm count/sperm motility." (PMID 38006387, 2023).
hypothyroidism (1 paper, 2015). Abnormally low levels of thyroid hormone. "The haplotype contains three genes (LHFPL5, SRPK1 and SLC26A8) with functions that are not explicitly obvious in the development of hypothyroidism." (PMID 26261983, 2015).
Shock (1 paper, 2022). The state in which profound and widespread reduction of effective tissue perfusion leads first to reversible, and then if prolonged, to irreversible cellular injury. "UPP1, S100A9, KIF1B, S100A12, SLC26A8 emerge remarkable diagnostic performance in pediatric septic shock and involved in immune cells infiltration." (PMID 36439140, 2022).
cancer (2 papers, 2021 to 2022). A tumor composed of atypical neoplastic, often pleomorphic cells that invade other tissues. "KRAS-mut cancers conserved a Ca++ transporter and anion transporter (SLC26A8) thought to be expressed only in sperm." (PMID 36612014, 2022).
tumor (1 paper, 2022). "On this basis, CD160, MMP-9, PTGDS, SLC26A8, and TLR5 were selected as indicators of tumor detection." (PMID 36733384, 2022).
SLC26A8 also shares sentences with these, for which no sentence is quoted: female sterility (1 paper); hereditary non-polyposis colorectal cancer (1); inflammatory bowel disease (1); nicotine addiction (1); Right ventricular cardiomyopathy (1); sterility (1); systemic lupus erythematosus (1).